BDNF (brain derived neurotrophic factor)
Diseases named in the same sentence as BDNF in open-access papers (continued):
Sharing a sentence is not in itself a finding about the gene and the disease.
glioma (113 papers, 2007 to 2026). A benign or malignant brain and spinal cord tumor that arises from glial cells (astrocytes, oligodendrocytes, ependymal cells). "The present study underscored the potential of BDNF as a diagnostic and prognostic biomarker in glioma." (PMID 39789839, 2025). "Multiple studies have demonstrated the importance of BDNF in gliomas and its association with the aggressiveness of the tumor." (PMID 39789839, 2025). "The univariate meta‐regression analysis revealed a significant association in glioma patients between the plasma mean levels of BDNF (outcome variable) and both age and female (covariates)." (PMID 39789839, 2025). "Overall, our findings underline the potential of tissue BDNF as a biomarker for glioma diagnosis and prognosis; however, cut‐off values, specificity, and sensitivity remain vague." (PMID 39789839, 2025). "To explore the intracellular consequences of BDNF-induced current amplification we performed in situ calcium imaging of xenografted glioma cells that express the genetically encoded calcium indicator GCaMP6s." (PMID 37914930, 2023). "Abrogation of activity-regulated BDNF secretion from the brain microenvironment or loss of glioma TrkB expression robustly inhibits tumour progression." (PMID 37914930, 2023). "IHC analysis 4, analyses stratified for IDH-mutation: In the analysis of IDH-WT gliomas, BDNF, CK2Beta and P-STAT5b were univariably associated (P < .1) with the domain executive functioning." (PMID 35148403, 2022). "Notably, an increased expression of brain-derived neurotrophic factor (BDNF) has been linked to the pathological advancement of gliomas." (PMID 38534769, 2024). "We observed elevated BDNF levels in patients with glioma-associated seizures at the time of diagnosis (P = 0.02) and during follow-up (P < 0.001), which aligns with the known activity-regulated release of BDNF, most likely from healthy neurons within high-neural glioblastoma networks." (PMID 38760585, 2024). "Additionally, increased brain-derived neurotrophic factor (BDNF) production stimulated by EE has been linked to reduced tumor growth in gliomas." (PMID 38003706, 2023). "Our meta‐analysis showed that glioma cases have significantly reduced BDNF plasma concentrations compared to controls, with lower levels in higher pathological grades, suggesting for the first time that plasma BDNF could be both a diagnostic and a prognostic marker in glioma." (PMID 39789839, 2025). "BDNF not only regulates the proliferation of healthy OPCs but also modulates the intensity of glutamatergic currents within glioma cells, reflecting the dynamic interplay between neurons and tumor cells." (PMID 40092993, 2025). "This systematic review and meta‐analysis evaluates peripheral and CNS BDNF levels in glioma patients." (PMID 39789839, 2025). "We calculated an SMD of −0.91 (95% CI: [−1.54, −0.27]) for this study, which also suggests a reduced BDNF level in CFS samples of glioma patients." (PMID 39789839, 2025). "BDNF regulates malignant synapse-like connections between neurons and glioma cells in malignant gliomas." (PMID 41018101, 2025). "This pathway produces brain‐derived neurotrophic factor (BDNF) that binds specifically to an NTRK2 receptor on Glioma Initiating Cells (GICs) which supports the growth of GICs." (PMID 40014265, 2025). "We calculated an SMD of 1.29 (95% CI: [0.28, 2.30]) for this study, which also suggests an elevated BDNF level in CFS samples of glioma patients." (PMID 39789839, 2025). "Brain-derived neurotrophic factor (BDNF) secreted by neurons amplifies current intensity in glioma cells, indicating dynamic connections between neurons and glioma cells." (PMID 40092993, 2025). "Across all comparisons, glioma cases had a reduced mean plasma BDNF concentration compared to the control group." (PMID 39789839, 2025). "Progesterone pre-treatment enhances serotonin-stimulated BDNF gene expression in rat C6 glioma cells through production of 5α-reduced neurosteroidsMorita and Her, 2008." (PMID 40141172, 2025).
glioma (continued). "Tissue BDNF levels were higher in glioma patients (SMD: 1.9513; 95% CI: [0.7365, 3.1661], p = 0.0016) and correlated with tumor grade (p = 0.0122)." (PMID 39789839, 2025). "Across multiple clinically and molecularly distinct forms of paediatric and adult gliomas, activity-regulated paracrine factors such as BDNF and shed neuroligin 3 promote glioma growth." (PMID 39972132, 2025). "We observed significant differences in both plasma and tissue levels of BDNF between glioma patients and healthy controls, with glioma patients having lower plasma concentrations and higher tissue concentrations." (PMID 39789839, 2025). "The reported findings regarding BDNF levels in the CSF of glioma patients compared to controls are somewhat contradictory." (PMID 39789839, 2025). "In all comparisons, glioma cases had higher average tissue levels of BDNF compared to the control group." (PMID 39789839, 2025). "This systematic review and meta‐analysis aim to investigate the potential of serum and tissue levels of BDNF as a biomarker in glioma." (PMID 39789839, 2025). "Meta‐analysis showed significantly reduced plasma BDNF levels in glioma patients versus controls (SMD: −1.0026; 95% CI: [−1.5284, −0.4769], p = 0.0002)." (PMID 39789839, 2025). "There is still a lack of systematic and comprehensive comparison of the sex‐specific alteration of BDNF concentrations among glioma patients." (PMID 39789839, 2025). "Three studies covering five comparisons between groups of glioma patients and healthy controls examined the plasma levels of BDNF." (PMID 39789839, 2025). "Six comparisons from four studies reported differences in tissue levels of BDNF in glioma patients compared to healthy controls." (PMID 39789839, 2025). "BDNF is a promising biomarker in glioma, showing significant changes in plasma and tissue levels correlating with tumor grade, patient age, and gender." (PMID 39789839, 2025). "Synaptogenic factors, such as neuroligin-3 and BDNF, further enhance glioma proliferation and synapse formation." (PMID 41595608, 2025). "BDNF signaling via the tropomyosin-related kinase B (Trk-B) receptor promotes trafficking of AMPA receptors to glioma cell membranes, thereby modulating the amplitude of postsynaptic currents." (PMID 41018101, 2025). "Our study also emphasized the clinical relevance of BDNF in glioma grading and highlighted its potential for improving diagnostic accuracy and prognosis assessment." (PMID 39789839, 2025). "BDNF also promotes synaptic connectivity between neurons and glioma cells by increasing AMPA receptor trafficking, thereby influencing the strength of these malignant synapses." (PMID 40685688, 2025). "Voluntary exercise decreased proliferation and supported self‐care in a glioma mouse model, possibly through increased BDNF attenuating proliferation." (PMID 40792048, 2025). "Following PRISMA guidelines, we systematically searched databases for studies measuring BDNF in glioma patients and controls." (PMID 39789839, 2025). "Mature BDNF and TrkB expression levels escalate with glioma malignancy grade, confirmed by immunostaining, RT‐qPCR, and ELISA (p < 0.001)." (PMID 39789839, 2025). "Although the Zheng and Chen (2020) study stated that they were investigating glioblastoma patients (which is glioma Grade IV by definition) for BDNF tissue levels, they also stated that the patients varied in Grades from I to IV." (PMID 39789839, 2025). "Previous research has identified the NTRK2-T1 isoform as dominant in glioma, playing a pivotal role in tumor growth and invasion through BDNF-TrkB regulation." (PMID 40133476, 2025). "The meta‐analysis showed that glioma cases have significantly reduced BDNF plasma concentrations compared to controls, with lower levels in higher pathological grades." (PMID 39789839, 2025). "(2004) both conducted a comparative analysis of BDNF levels in the CSF of glioma patients compared to healthy individuals." (PMID 39789839, 2025).
glioma (continued). "The rat C6 glioma cells of the 5 and 10 μM Anax imperator adipokinetic hormone groups showed significantly high expressions of brain-derived neurotrophic factor and migrasomes numbers, compared with the control group." (PMID 38775506, 2024). "Quantitative RT-qPCR analysis disclosed the expression levels of hsa-miR-134-5p downregulation and BDNF upregulation mRNA across two glioma cell lines (U251, U87), a contrast to that observed in normal human astrocytes (NHAs)." (PMID 38579169, 2024). "Scheme of the experiment of introduction GQIcombi (bi-(AID-1-T) + SB431542, LDN-193189, purmorphamine, and BDNF) into rat glioma 101/8." (PMID 38988707, 2024). "While NLGN3 also possesses the capability to stimulate synapse formation between neurons and gliomas, its proliferative effect on pediatric cortical high‐grade gliomas (pHGGs) is relatively less pronounced compared to BDNF." (PMID 39469896, 2024). "BDNF regulates cell growth, differentiation, migration and apoptosis in the nervous system and high-grade gliomas." (PMID 38455766, 2024). "Signaling through the receptor TrkB to CAMKII, BDNF facilitates the trafficking of AMPA receptors to the glioma cell membrane." (PMID 38534769, 2024). "The aim of this study was to investigate the effects of Ani-AKH on BDNF expression and ultrastructure of cells in the rat C6 glioma cell line using immunocytochemistry and transmission electron microscope." (PMID 38775506, 2024). "Investigations have substantiated that BDNF serves as a potent activator of signaling cascades such as BDNF/TrkB/PI3K/Akt and TrkB/ATF4, effectively counteracting the inhibitory and apoptotic impacts of BDNF inhibitors on C6 glioma cells." (PMID 39469896, 2024). "AMPAR trafficking to the glioma cell membrane is promoted by docking of BDNF to the receptor NTRK2, resulting in an increased amplitude of glutamate-evoked currents in the malignant cells." (PMID 38834748, 2024). "Our research investigated the effects of hsa-miR-134-5p on glioma progression, focusing on its interaction with the BDNF/ERK signaling pathway." (PMID 38579169, 2024). "This intricate interplay between neurons and glioma cells, mediated by paracrine signals such as BDNF, NLGN3, and IGF‐1, underscores the complexity of the TME in brain tumors and highlights potential therapeutic targets for future interventions." (PMID 39469896, 2024). "The findings from this study also suggest the possible use of the new therapeutic targets such as BDNF and formation of migrasome in the glioma treatment." (PMID 38775506, 2024). "In the context of gliomas, these tumors exploit BDNF's mechanisms to their advantage, mimicking the healthy brain's developmental pathways." (PMID 39469896, 2024). "In this study, the rat C6 glioma cells induced by Ani-AKH showed high expression of BDNF and formation of migrasomes in the Ani-AKH-5 and Ani-AKH-10 groups compared to the control group." (PMID 38775506, 2024). "In brief, neuronal activity arising from glioma-to-neuron interactions during tumor growth or seizure initiation seems to be a pivotal driver for BDNF release and identifies a potential biomarker of high-neural glioblastoma." (PMID 38760585, 2024). "Neuronal release of activity-dependent soluble factors, such as glutamate, neuroligin-3 (NLGN3), and brain-derived neurotrophic factor (BDNF), promote glioma progression." (PMID 38193532, 2024). "Paracrine signaling is the neuronal activity that propels tumor progression, in the context of gliomas, via neuroligin-3 and BDNF, as well as through neuron-glioma synapses mediated by AMPA receptors, synapses which are modulated by BDNF." (PMID 38534769, 2024). "Mature BDNF activates TrkB receptor with high affinity on glioma surface, thereby promoting cell survival." (PMID 39469896, 2024). "A similarly modest increase in proliferation was observed in a range of patient-derived glioma monocultures exposed to BDNF, including thalamic DMG and paediatric cortical glioblastoma." (PMID 37914930, 2023).
glioma (continued). "Treatment with the pan-Trk inhibitor entrectinib abrogated this BDNF-induced increase in GluA4 phosphorylation in glioma cells." (PMID 37914930, 2023). "Neuronal activity promotes glioma growth through both paracrine signalling (neuroligin-3 and brain-derived neurotrophic factor (BDNF)) and AMPAR (α-amino-3-hydroxy-5-methyl-4-isoxazole propionic acid receptor)-mediated excitatory electrochemical synapses." (PMID 37138086, 2023). "Testing the effects of BDNF alone on glioma proliferation in vitro, we found that the addition of recombinant BDNF (100 nM) increases paediatric glioma (DIPG) cell proliferation from a rate of around 20% to around 30%." (PMID 37914930, 2023). "Our findings contrasted with previous in vitro studies, which showed that BDNF expression was upregulated in human glioma tissues compared to normal brain tissues." (PMID 38050515, 2023). "Genetic expression patterns of the neurotrophin receptors in DMG tumours, suggests that BDNF acts on glioma cells through the TrkB (encoded by NTRK2) receptor and that BDNF is a key neurotrophin to which paediatric glioma cells respond." (PMID 37914930, 2023). "Together, these findings demonstrate that the BDNF–TrkB signalling pathway modulates the strength of glutamate-evoked currents in glioma cells." (PMID 37914930, 2023). "This is in line with several studies, which showed that valproates significantly increase GDNF and BDNF expression in rat C6 glioma cells and astrocytes." (PMID 38069144, 2023). "The intensity and duration of glutamate-evoked calcium transients were increased by BDNF exposure in two distinct patient-derived models of paediatric glioma." (PMID 37914930, 2023). "Optogenetic promotion of optic pathway glioma growth was mediated in these low-grade gliomas by BDNF and NLGN3 secretion, which in turn was promoted by retinal activity." (PMID 36968288, 2023). "Together, these data demonstrate that BDNF–TrkB signalling modulates neuron-to-glioma synaptic connectivity." (PMID 37914930, 2023). "Signalling through the receptor tropomyosin-related kinase B16 (TrkB) to CAMKII, BDNF promotes AMPA receptor trafficking to the glioma cell membrane, resulting in increased amplitude of glutamate-evoked currents in the malignant cells." (PMID 37914930, 2023). "NT-4, a neurotrophin that also signals through TrkB, promotes glioma proliferation similarly to BDNF." (PMID 37914930, 2023). "To test the effects of BDNF on neuron-to-glioma synaptic currents, we stimulated the axonal afferents (Schaffer collaterals) into the CA1 region of the hippocampus in which glioma cells were engrafted." (PMID 37914930, 2023). "We sought to investigate the relative contribution of BDNF–TrkB signalling in neuron–glioma interactions using neuronal co-culture with NTRK2 wild-type or NTRK2-KO glioma cells." (PMID 37914930, 2023). "The study of paracrine interactions between the nervous system and glioma cells has centered on the roles of brain-derived neurotrophic factor (BDNF) and neuroligin 3 (NLGN3)." (PMID 36968288, 2023). "Blocking TrkB genetically or pharmacologically abrogates these effects of BDNF on glioma synapses and substantially prolongs survival in xenograft models of paediatric glioblastoma and diffuse intrinsic pontine glioma." (PMID 37914930, 2023). "A negative regulatory correlation between miR-103 and the BDNF mRNA and protein expression levels has been reported in gliomas." (PMID 35916975, 2022). "Overexpression of miR-103 inhibits the proliferation and invasion of cancer cells in patients with gliomas through downregulation of BDNF." (PMID 35916975, 2022). "Brain-derived neurotrophic factor (BDNF) is widely distributed in the central nervous system, affecting the malignant degree of glioma." (PMID 35872846, 2022). "Su and colleagues also demonstrated that PGRMC1 mediated the progesterone-induced release of neurotrophic BDNF in rat C6 glioma cells via activation of the ERK5 signaling pathway." (PMID 36266625, 2022).
glioma (continued). "BDNF-AS1 repression upregulates BNDF expression and activates the brain-derived neurotrophic factor, which is a protective modulator in several gliomas." (PMID 35054945, 2022). "For instance, application of conditioned media containing BDNF to glioma cell cultures leads proliferation of glioma cells, which is effectively suppressed through inhibition of TRKB (the receptor for BDNF)." (PMID 35898410, 2022). "Rs4702‐A was significantly associated with increased expression of FURIN and BDNF in the serum and PBMC of glioma patients after radiotherapy." (PMID 34953024, 2022). "Silencing P2X4R interrupts the proliferation of glioma cells by downregulating the BDNF/TrkB/ATF4 pathway." (PMID 35372041, 2022). "In particular, glioma cells likely take advantage of the secretion of trophic factors, such as brain-derived neurotrophic factor (BDNF) and neuroligin-3 (NLGN3), which are regulated by neuronal activity." (PMID 35740334, 2022). "In vitro studies demonstrate that BDNF, through its receptor TrkB, stimulates high grade glioma cells proliferation and that BDNF release increases with neural activity." (PMID 34690699, 2021). "BDNF infusion was also found to reduce TAMs infiltration and activation, and to dampen glioma migration via inhibition of RhoA through the truncated TrkB.T1 receptor." (PMID 34690699, 2021). "TEA increased the levels of phospho-ERK and phospho-Akt, improved CREB phosphorylation at Ser133, and, thus, enhanced the release of BDNF in rat glioma cells C6." (PMID 34975553, 2021). "The luciferase assay reveals that syncytin-1 significantly activates BDNF promoter activity in human U251 glioma cells." (PMID 35059135, 2021). "TrkB, via its activating ligand brain-derived neurotrophic factor (BDNF), plays a pivotal role in neuronal survival, and increasing evidence also supports a role for TrkB signaling in glioma cell growth." (PMID 33673213, 2021). "SPIONs drive miR-485-5p overexpression in cells and inhibit endogenous Tie1 expression to downregulate the protein expression levels of Fgf2/GDNF/GFAP/BDNF and significantly weaken the in vivo and in vitro viability of gliomas." (PMID 32174801, 2020). "For example, the brain-derived neurotrophic factor (BDNF) secreted by differentiated glioma cells activates the neurotrophic receptor kinase 2 (NTRK2) expressed on GSCs, which promotes the activation of AKT pathways in the process of survival of GSCs68." (PMID 32595946, 2020). "The induction of BDNF was also shown to be central for the anti-tumorigenic activity of oleandrin in a murine model of glioma." (PMID 31824586, 2019). "It has been reported previously that ketamine treatment resulted in an NMDA receptor-independent induction of cAMP signaling in C6 glioma cells, which, in turn, increased BDNF expression." (PMID 31554266, 2019). "BDNF enriched in glioma environment stimulated the production of IL-15 in CD11b+ macrophages cells and altered macrophage plasticity." (PMID 30034397, 2018). "All these factors suggest that BDNF participates in the progression of glioma by regulating these oncogenic kinases." (PMID 30233327, 2018). "GAMs, stimulated by brain-released BDNF, induced IL-15 production and, consequently, increased NK cells’ infiltration and activation, contributing to limit glioma expansion." (PMID 30123112, 2018). "It has been reported that the Src and Akt are common downstream signaling kinases of BDNF, so these findings are consistent with the increase of BDNF in glioma patients." (PMID 30233327, 2018). "We demonstrate that BDNF stimulated the production of IL-15 in the brain of glioma-bearing mice, and specifically in microglia upon challenge with IL-4 or co-culture with glioma cells." (PMID 29286001, 2017). "We investigated the possible effects of BDNF on glioma biology, demonstrating that the infusion of BDNF in mouse brain induces IL-15 production by CD11b+ cells." (PMID 29286001, 2017).